RN7SL145P (RNA, 7SL, cytoplasmic 145, pseudogene)
Gene: Miscellaneous RNA gene on chromosome 3 (45,742,675 to 45,742,970, forward strand). Ensembl gene ENSG00000244357.
Homologues: Orthologues: chimpanzee Metazoa_SRP (99% identical), macaque Metazoa_SRP (97% identical). Paralogues in human: RN7SL2 (86% identical), RN7SL1 (85% identical), RN7SL147P (84% identical), RN7SL3 (84% identical), RN7SL398P (83% identical), RN7SL14P (82% identical), RN7SL296P (82% identical), RN7SL650P (82% identical), RN7SL655P (82% identical), RN7SL665P (82% identical), RN7SL220P (81% identical), RN7SL44P (81% identical), and 704 more.